CD14 (CD14 molecule)
Diseases named in the same sentence as CD14 in open-access papers (continued):
Sharing a sentence is not in itself a finding about the gene and the disease.
sarcoidosis (18 papers, 2012 to 2026). Sarcoidosis is a multisystemic disorder of unknown cause characterized by the formation of immune granulomas in involved organs. "HIF-1α expression has recently been found to be upregulated in sarcoidosis CD14 monocytes and associated with regulation of IL-1β and IL-17 production; here, we confirmed upregulation of HIF1A in these cells." (PMID 33363531, 2020). "To test a potential direct contribution of macrophages in sarcoidosis granuloma formation, we obtained CD14+ blood monocytes and differentiated them into macrophages with GM-CSF for phenotypic observation and transcriptomic profiling." (PMID 38353578, 2024). "For example, here, among other genes, STAT1, IL10RA, and PTEN were underexpressed in sarcoidosis CD14 monocytes compared to controls while CXCR4, ATG12, HIF1A, CCR1, and IER3 were overexpressed, consistent with the effects of TGFB1 signaling." (PMID 33363531, 2020). "To determine the effect of GCs on transcriptome profiling of sarcoid AMs and CD14+ monocytes, we compared the RNA-seq data of sarcoidosis AMs and CD14+ cells treated with dexamethasone in vitro vs. untreated sarcoidosis AMs and CD14+ monocytes, respectively." (PMID 32477331, 2020). "We performed transcriptomic analysis of isolated AMs and CD14+ monocytes from the same sarcoidosis patients in response to ex-vivo treatment with DEX." (PMID 32477331, 2020). "Flow cytometry was performed to analyse TREM-1 and TREM-2 expression on CD14+ cells in bronchoalveolar lavage fluid from patients having sarcoidosis or HP and a control group." (PMID 32508528, 2020). "To decrease the confounding factors related to human genetic variation, we isolated the CD14+ peripheral blood monocytes and AMs from the BALs of the same sarcoidosis subjects and compared pairwise RNA seq results." (PMID 32477331, 2020). "To identify genes responsive to GC on sarcoidosis monocytes, we isolated CD14+ monocytes from PBMCs and treated in a similar fashion with DEX." (PMID 32477331, 2020). "We determined and compared the whole transcriptional signatures of alveolar macrophages from sarcoidosis patients and blood CD14+ monocytes of the same subjects in response to in vitro treatment with dexamethasone (DEX) via RNA-sequencing." (PMID 32477331, 2020). "We also demonstrated that in patients with sarcoidosis the intermediate CD16+ CD14++ blood monocyte population was expanded." (PMID 27929051, 2016). "Monocytes appeared to be responsible for elevated TNF and IL-6 responses in sarcoidosis patients, so monocyte subsets were characterised based on relative expression of CD14 and CD1624." (PMID 27929051, 2016). "Peripheral blood cells of sarcoidosis patients and healthy controls were stained for the markers HLA-DR, CD14, CD16, CD120a and CD120b." (PMID 23039818, 2012). "Treatment was not responsible sarcoidosis-associated CD14 monocyte dysregulation; treatment led to the reversal of the direction of the enrichment of the majority of pathways." (PMID 33363531, 2020). "Moreover, enhanced TNF-α expression has also been linked to CD14+ monocytes in non-Löfgren and pulmonary monocytes in progressive phenotypes of sarcoidosis." (PMID 36311769, 2022). "Protein concentrations of pro-inflammatory cytokines CD14 and Cystatin C have been shown to be elevated in multiple inflammatory disorders and were also elevated in the LDL fraction in sarcoidosis patients compared to healthy controls." (PMID 38627696, 2024). "Clusters #6074, #6025, #6066, and #6054 were prevalent in sarcoidosis and characterized by CD64+ CD11blo CD14– CD223(LAG3)+ HLA-DR+ CD163hi expression." (PMID 36949950, 2023). "From queried PBMC subsets, only significantly increased CD14+ monocyte and significantly decreased CD4+ T-cell proportions were noted in sarcoidosis when compared against controls within both cohorts (MWU test p-value <0.05)." (PMID 36311769, 2022).
sarcoidosis (continued). "CD14+CD16+ intermediate monocytes, a subset of monocytes, are expanded in circulation of sarcoidosis patients, probably due to the systemic inflammation, as observed in other inflammatory diseases." (PMID 33446605, 2021). "We found still much higher TREM-1 expression in sarcoidosis compared with HP and the difference was statistically significant (percentage of TREM-1+CD14+ cells: P = 0.0002; TREM-1 MFI P = 0.0395)." (PMID 32508528, 2020). "Data mining of our RNA-Seq analysis of CD14+monocytes showed enrichment for metabolic and hypoxia inducible factor (HIF) pathways in sarcoidosis." (PMID 30946009, 2019). "We found that a higher percentage of CD14+ monocytes express HIF-1α and HIF-2α in sarcoidosis subjects as compared to controls." (PMID 30946009, 2019). "Notably, CD14+ pro‐inflammatory monocytes (CD14+FCGR3A−IL1B+) are rare in healthy donors but increased in patients with active TU and sarcoidosis compared with healthy donors." (PMID 40469525, 2025). "To identify pathways involved in in vitro granuloma formation, we performed bulk RNA sequencing on isolated CD14+ monocytes and GM-CSF induced MDMs obtained from 5 sarcoidosis patients and 4 non-sarcoidosis controls." (PMID 38353578, 2024). "Interestingly, despite cohort heterogeneity, CD14+ monocyte and CD4+ T-cell proportions in sarcoidosis cases and controls were comparable between cohorts." (PMID 36311769, 2022). "In this study, we hypothesized that sarcoidosis macrophages are intrinsically prone to form granulomas and sought to culture them in vitro from sorted CD14+ monocytes without the presence of T cells." (PMID 38353578, 2024). "In sarcoidosis patients there was expansion of the intermediate CD14++/CD16+ monocyte population (13.6% ± 1.01 (mean ± SEM) compared with 9.3% ± 0.82, p < 0.05) and reduction in classical CD14++/CD16− monocytes (78.1% ± 1.13 compared with 83.6% ± 2.01, p < 0.01)." (PMID 27929051, 2016).
ischemic stroke (17 papers, 2008 to 2025). A stroke disorder caused by obstruction of blood flow to the brain, due to thrombotic (local blood clot formation) or embolic (due to a blood clot or other material traveling from another site) event. "Increased levels of cystatin C, serpin F2, and CD14 were associated with an increased risk of MI, vascular events and all-cause mortality, whereas increased protein content of CD14+ EVs also correlated with a higher risk of an ischemic stroke." (PMID 31920664, 2019). "Previously, we identified the human orthologues for a number of rat genes, which expression was changed after ischaemic stroke (Adora2a, Bcl3, Ccl22, Ccr1, Cd14, Gpr6, Gpr88, Rgs9, and other genes)." (PMID 34946819, 2021). "An increased percentage of CD163+/CD16+ and CD163+/CD14++ events was found 24 and 48 h after an ischemic stroke when compared to control subjects (CT)." (PMID 34201498, 2021). "An initiation of the Tlr signaling can occur through transfer of bacterial LPS, particularly as plasma levels of LPS are elevated in ischemic stroke, by Lbp to a receptor complex that localizes on microglia and includes Tlrs (the most known Tlr4) and co-receptor CD14." (PMID 34944656, 2021). "Based on the results of immune infiltration and single-cell analysis, the exosome-related feature genes identified in this study (LGALS3, CD14, TLR2) regulate the neuroinflammatory process following ischemic stroke through multidimensional mechanisms." (PMID 40458459, 2025). "The LPS-NC, LPS-binding protein (LBP), soluble CD14 (sCD14), lipoprotein profiles, apo(lipoprotein) A-I, apoB, and phospholipid transfer protein (PLTP) activity, were determined in 98 ischemic stroke patients and 100 age- and sex-matched controls." (PMID 32084157, 2020). "Specifically, clinical studies in ischaemic stroke and ICH have reported an expansion of classical (CD14+CD16−) and intermediate (CD14+CD16+) populations at the expense of non-classical monocytes (CD14loCD16+)." (PMID 36346451, 2023).
pancreatic cancer (17 papers, 2014 to 2024). "Then, pancreatic cancer cells were cocultured with CD14+ monocytes, which can differentiate into macrophages." (PMID 38575607, 2024). "One study observed that CD14+ human peripheral blood mononuclear cells (PBMCs), when co-cultured with fibroblasts from pancreatic cancer tissue, exhibited an increased expression of M2 macrophage phenotype markers CD163 and CD206." (PMID 37108548, 2023). "EpCAM+ cancer cells (PD-L1− or TIM-3−), CD8+ T cells with either PD-1+ or TIM-3+, and CD14+CD68+CD163+TIM-3+ macrophages increased in the MPE of a patient with progressive pancreatic cancer." (PMID 36293034, 2022). "A lower frequency of peripheral blood CD14+CD16– monocytes was associated with their increase in bone marrow and greater survival in pancreatic cancer, suggesting that pancreatic tumors systemically alter monocyte trafficking." (PMID 30776148, 2019). "We previously showed that the stromal compartment of colorectal and pancreatic cancers contain CD14+ monocytic cells expressing S100A8 and S100A9 proteins." (PMID 30558665, 2018). "Increased population of CD14+ monocytes and CD11C+ dendritic cells were also documented with gemcitabine treatment in patients with advanced pancreatic cancer." (PMID 25889536, 2015). "In advanced pancreatic cancer patients, GEM therapy may decrease memory T-cells, promote naive T-cell activation, and induce the proliferation of CD14+ monocytes and CD11c+ DC." (PMID 31440238, 2019). "Third, we found upregulation of the CD33 transcript, but not of CD14, suggesting the presence of myeloid-derived suppressor cells (MDSCs), previously reported as increased in pancreatic cancer." (PMID 27589570, 2016). "The genes overexpressed in the PDL1-up group of pancreatic cancers also included CD33, but not CD14, which is concordant with the presence of myeloid-derived suppressor cells (MDSCs)." (PMID 27589570, 2016).
pulmonary TB (17 papers, 2012 to 2025). "A 6-protein diagnostic panel, comprising FETUB, FCGR3B, LRG1, SELL, CD14, and ADA2, differentiated patients with pulmonary TB from healthy controls and patients with other respiratory infections with high sensitivity and specificity in both cohorts." (PMID 38512356, 2024). "Expressions of PD-L1 on CD14+ monocytes in pulmonary TB patients before treatment were significantly lower in cases with 1-month or 2-month smear conversion, and 1-month culture conversion compared to those without smear/culture conversion." (PMID 35163542, 2022). "The increased expression of PD-1 on CD4+ T cells and PD-L1 on CD14+ monocytes was evident in pulmonary TB patients, and the increased expression of PD-L1 on CD14+ monocytes was associated with higher bacterial burden and delayed smear/culture conversion." (PMID 35163542, 2022). "Patients with untreated pulmonary tuberculosis were reported to have decreased IFNGR1 expression on circulating CD14+ monocytes compared to healthy uninfected controls." (PMID 28542482, 2017). "Our results displaying a decrease in HLA-DR+ and CD86+ monocytes and an increase in CD14+CD16+ cells in pulmonary tuberculosis confirm the results of other investigators." (PMID 26339660, 2015). "In the present study, in addition to increased expression of PD-L1 on monocytes in active TB patients, the expression of PD-L1 on CD14+ monocytes was significantly higher in smear-positive pulmonary TB patients and those with delayed sputum smear/culture conversion." (PMID 35163542, 2022). "In this respect our data showing a more pronounced augmentation of CD14+CD16+ monocytes in PPD-anergic patients which differ by higher severity is still another argument of an unfavorable prognostic role of CD16+ monocytes in pulmonary tuberculosis." (PMID 26339660, 2015). "Walzl’s group showed a high frequency of CD14+ MDSCs in pleural TB, suggesting that pulmonary and extra-pulmonary TB could induce different MDSC subset expansion." (PMID 25879532, 2015). "The expression of PD-L1 on CD14+ monocytes and PD-1 on CD4+ T cells are significantly higher in human pulmonary TB cases and positively correlated with higher bacterial burden and worse treatment outcomes." (PMID 40137709, 2025). "The expression of PD-L1 on CD14+ monocytes was significantly higher in pulmonary TB patients compared with non-TB, non-LTBI individuals (p = 0.012)." (PMID 35163542, 2022). "The expression of PD-1 and PD-L1 on CD4+ T cells, CD8+ T cells, and CD14+ monocytes in PBMCs from pulmonary TB patients, LTBI cases, and non-TB, non-LTBI individuals was measured by flow cytometry." (PMID 35163542, 2022). "It was noted that in the new-onset patients with pulmonary tuberculosis, thick-walled bacilli were negatively correlated with CD4+/CD8+ and CD14+CD16+ and are positively correlated with CD14+CD16-; at the genus level, Enterococcus faecalis was positively correlated with CD4+/CD8+ and CD4+43." (PMID 35383237, 2022). "Individual variation was large, but blood of TBM and pulmonary tuberculosis patients showed a consistently stronger myeloid response compared to healthy controls, with increased numbers of mature (CD16+) neutrophils and classical (CD14++CD16−) monocytes." (PMID 30696839, 2019). "CD14 analysis was not performed in the pulmonary TB patients, even if a heterogeneous morphology (granulocytic and monocytic) was described by light microscopy on HLA-DR-/CD33+ isolated cells." (PMID 25879532, 2015). "Compared to control cell cultures, CD14+ cells induced by Mtb displayed similar MFI expression of CD11b, HLA-DR, CD64 and CD16 surface molecules and most, but not all experiments presented increased frequency of CD14+CD16+ monocytes, which were previously associated with severe pulmonary TB." (PMID 31637998, 2019).
steatosis (17 papers, 2013 to 2025). Increased lipid within the cytoplasm of cells. "LPS can cleave membrane-bound CD14 (mCD14), releasing presepsin into circulation, while CD14 depletion reduces liver lipids and macrophage content, ultimately alleviating steatosis." (PMID 41190061, 2025). "FOS ameliorated hepatic inflammation by reducing the expression of TLR4 and CD14, and improved steatosis and tight junctions by regulating the production of SCFAs." (PMID 35211093, 2022). "Collectively, restoration of the levels of serum CD14 and LPS, proinflammatory cytokines, SCFAs, and LCFAs contributes to the improved inflammation and steatosis in the livers of sucralose-treated mice after metformin or FOS supplementation." (PMID 33622853, 2021). "FSTL1 could not restore cellular lipid accumulation and lipid metabolism gene expression in Dip2a or Cd14 knockdown AML12 steatosis cells co-cultured with GAS from F4MKO mice." (PMID 37770480, 2023). "Enhanced expression of leptin-induced hepatic CD14 may increase hepatic responsiveness to even low levels of gut microbiota-derived endotoxins, which may prompt the progression of simple steatosis to NASH via STAT3 signaling." (PMID 34777261, 2021). "In chow-fed mice Leptin increased hepatic expression of CD14 via STAT3 signaling and hyperreactivity against low-dose LPS without steatosis, while leptin-deficient ob/ob mice with severe steatosis had a marked decrease in hepatic CD14." (PMID 32823983, 2020). "However, db/db and ob/ob mice presented a decrease in hepatic CD14 expression and a decrease in responsitivity to bacterial endotoxin despite the severe obesity and steatosis." (PMID 33316927, 2020). "Inhibition of CD14 expression is critical for the progression from steatosis to steatohepatitis." (PMID 26911834, 2016). "Moreover, upregulation of CD14 in KCs and hyperreactivity against low-dose LPS were observed in high-fat diet-induced steatosis in mice." (PMID 26629827, 2015). "Imajo and colleagues documented CD14-positive Kupffer cells in the experimental model of steatosis." (PMID 24016701, 2013). "Interestingly, several proteins associated with steatosis and fibrosis were significantly correlated with markers of cholesterol metabolism (VLDL, HDL, triglycerides), inflammation (CD14, CD163, IL6), as well as cardiometabolic diseases, HIV-specific parameters, and ART, but not with SNPs." (PMID 39426127, 2024). "Chow-fed control mice did not have a similar effect and leptin increased hepatic expression of CD14 via STAT3 signaling and hyperreactivity against low-dose LPS without steatosis, while leptin-deficient ob/ob mice with severe steatosis had a marked decrease in hepatic CD14." (PMID 35052763, 2021). "Thus, enhanced expression of hepatic CD14 by leptin may increase hepatic responsiveness to gut microbiota-derived endotoxins even at low levels, resulting in the progression from simple steatosis to NASH via STAT3 signaling." (PMID 34360923, 2021). "Mice receiving a high-fat diet (HFD) develop steatosis and accelerated NASH progression with liver inflammation and fibrosis and upregulation of CD14 in Kupffer cells and hyperreactivity against low-dose LPS." (PMID 35052763, 2021). "Leptin and STAT3 signaling increased the responsiveness to gut-derived, low-dose bacterial endotoxin even in the healthy liver via an increase in CD14-positive Kupffer cells, regardless of the presence of steatosis." (PMID 34360923, 2021). "In summary, we showed that, in a mouse model of NASH/NAFL, RSV administration can improve inflammation and fibrosis, but not steatosis, via inhibition of LPS reactivity that is due to CD14 expression in Kupffer cells." (PMID 26911834, 2016). "Indeed, when leptin was co-administrated in chow-fed mice also induced the upregulation of CD14 in Kupffer cells, which could lead to hepatic inflammation and fibrosis in the absence of steatosis." (PMID 33316927, 2020).
steatosis (continued). "Despite exhibiting improvement of steatosis, PNS produced no significant change in hepatic CD14 and TLR4 expression in ob/ob mice." (PMID 33656663, 2021). "Taken together, these results demonstrate that CD4+ T cells, but not CD8+ T cells or CD14+ monocytes, contribute to the development of NAFLD-induced inflammation and steatosis-to-fibrosis progression." (PMID 33013934, 2020). "Upregulation of CD14 in Kupffer cells and hyperreactivity against low-dose LPS occurred in high-fat diet (HFD)-induced steatosis mice, but not chow-fed-control mice." (PMID 32823983, 2020). "The upregulation of CD14 by leptin-mediated signaling in Kupffer cells is critical in regulating the hepatic inflammatory response to the bacteria-mediated progression of NASH, although even in a healthy liver may exist an activation of this via irrespective of the presence of steatosis." (PMID 33316927, 2020).